FGF23 (fibroblast growth factor 23)
Diseases named in the same sentence as FGF23 in open-access papers (continued):
Sharing a sentence is not in itself a finding about the gene and the disease.
Abdominal obesity (8 papers, 2017 to 2025). Excessive fat around the stomach and abdomen. "Another study conducted in 1599 normoglycemic individuals, including men and premenopausal and postmenopausal women, found independent associations between the presence of abdominal obesity and increased serum levels of FGF23 in specific groups." (PMID 38732094, 2024). "FGF23, on the other hand, shows positive associations with central and abdominal obesity." (PMID 39329699, 2024). "In addition, we have also found that serum FGF23 levels are closely associated with the presence of abdominal obesity." (PMID 28619026, 2017). "The presence of abdominal obesity and the increase in serum FGF23 levels in men and postmenopausal women." (PMID 35053218, 2022). "Consistent with these previous findings, serum FGF23 levels were independently and positively related to W in the present study, reminding that abdominal obesity should be taken into consideration when exploring abnormal serum FGF23 levels." (PMID 28619026, 2017). "Serum FGF23 levels are elevated in obese individuals, especially those with abdominal obesity." (PMID 35053218, 2022). "On the other hand, the high-FGF-23 group had 5 mmHg lower systolic blood pressure on average (p-value = 0.041), had a lower average body mass index by 1 kg/m2 (p-value = 0.039), and about 15% less central obesity (p-value = 0.04)." (PMID 36671416, 2022).
dental abscesses (8 papers, 2019 to 2024). "This elevation may contribute to poor dentin mineralisation and, thus, increased susceptibility to periapical abscesses, independent of FGF23 or phosphate involvement." (PMID 38821917, 2024). "The authors hypothesized that the immune response may be improved by decreasing FGF-23 serum levels with Burosumab treatment, which may reduce the occurrence of dental abscesses, since high FGF-23 serum levels have been shown to correlate with an increased risk of infection." (PMID 38137614, 2023). "Burosumab, by targeting the excessive FGF23 in XLH, may improve the immune response to endodontic infection and reduce the occurrence of dental abscess." (PMID 36398111, 2022). "Although improvement of dental abscesses has been reported under conventional therapy at least in adults, FGF23-blocking antibody treatment studies did not investigate dental symptoms in detail and did not reveal a reduction in dental symptoms in adverse events." (PMID 31993875, 2020). "Contrasting the high frequency of dental abscesses in Hyp mice with their relative absence in Phex- and Fgf23-normal hypophosphatemic mouse models or in HHRH patients indicates that a phosphate-independent mechanism is likely to contribute to formation of dental abscesses in XLH." (PMID 30808384, 2019).
Hyperinsulinemia (8 papers, 2013 to 2025). An increased concentration of insulin in the blood. "This small but significant increase in serum iFGF23 induction by hyperinsulinism in patients with T2DM under euglycemic conditions points to the contribution of insulin to FGF23 production." (PMID 34208131, 2021).
hyperuricemia (8 papers, 2016 to 2024). An abnormally high level of uric acid. "FGF-23 was positively correlated with the occurrence of hypercholesteremia (P < 0.001), hyperuricemia (P = 0.022) and family history of CHD (P = 0.022)." (PMID 33413149, 2021). "Furthermore, FGF-23 was positively correlated with hypercholesteremia, hyperuricemia and family history of CAD (all P < 0.05)." (PMID 33413149, 2021). "Consequently, we hypothesize that the negative correlation between plasma S-Klotho levels and hyperuricemia may be owing to the FGF23/S-Klotho endocrine axis, and this may also explain the saturation effect between S-Klotho and hyperuricemia from another aspect." (PMID 36411464, 2022). "Alternatively, it is likely that other factors (other than hyperuricemia) are predominantly responsible for reduced vitamin D activation in CKD, such as reduced nephron mass or increased FGF-23." (PMID 30356327, 2018). "Patients with hyperuricemia had lower eGFR and significantly higher levels of FGF23 and TNF-α than those without hyperuricemia." (PMID 39768960, 2024). "Patients with hyperuricemia had significantly higher values of FGF23 and TNF-α compared with those without hyperuricemia." (PMID 39768960, 2024).
multiple myeloma (8 papers, 2015 to 2024). "Additionally, FGF23 and phosphate have emerged as relevant factors in cancer pathophysiology, particularly in cancer types with implications for bone health such as bone sarcoma, multiple myeloma, or those associated with bone metastases." (PMID 38792509, 2024). "Yet, multiple myeloma (MM) cancer cells exhibit a response to FGF23, probably released by bone cells." (PMID 38397231, 2024). "FGF23 is particularly significant for those forms of cancer primarily affecting bone (e.g., multiple myeloma) or characterized by bone metastasis." (PMID 33520985, 2020). "Our results suggest that FGF23 from skeletal osteocytes drives a vicious cycle of myeloma growth in bone by binding to MM cells and activating transcription of pro-metastatic and pro-osteolytic genes, such as heparanase." (PMID 25944690, 2015). "To test if FGF23 activates signaling in myeloma cells, we assessed EGR1, an early response transcription factor induced by FGF23 in kidney tubules." (PMID 25944690, 2015). "Multiply myeloma (MM) grows in and destroys bone, where osteocytes secrete FGF23, a hormone which affects phosphate homeostasis and aging." (PMID 25944690, 2015). "FGF23 messenger RNA was undetectable (four myeloma cell lines) or much lower (four primary patient samples) than the positive bone control." (PMID 25944690, 2015). "Bone expression of FGF23 mRNA was significantly increased 2-5 fold after one week of co-culture with myeloma cells." (PMID 25944690, 2015). "We report that multiple myeloma (MM) cells express receptors for and respond to FGF23." (PMID 25944690, 2015). "Next we tested if an inhibitor of FGF23 signaling altered myeloma growth in bone." (PMID 25944690, 2015). "The presence of myeloma cells could stimulate osteocyte secretion of FGF23, leading to its elevation in patient sera." (PMID 25944690, 2015). "Studies are under way to identify myeloma-derived factors that increase FGF23 production." (PMID 25944690, 2015). "Furthermore, FGF23 and phosphate have emerged as pertinent factors in cancer pathophysiology, with FGF23 being particularly relevant for cancer types that predominantly affect bone health (e.g., multiple myeloma) or exhibit bone metastases." (PMID 38792509, 2024). "Moreover, osteocyte-derived FGF23 may activate the transcription of pro-metastatic and pro-osteolytic genes in another neoplasm with skeletal involvement, such as multiple myeloma." (PMID 38806758, 2024). "Furthermore, it appears that multiple myeloma cells themselves express receptors for FGF-23." (PMID 37342302, 2023). "It is not possible to distinguish myeloma cells being devoid of FGF23 mRNA but contaminated with bone cells, versus low expression of FGF23 by MM cells." (PMID 25944690, 2015). "In multiple myeloma (MM), FGF23 is not expressed by cancer cells." (PMID 38397231, 2024).
osteoglophonic dysplasia (8 papers, 2013 to 2025). A rare skeletal disorder characterized by dwarfism, severe craniofacial abnormalities and multiple unerupted teeth. "In this regard, FGF23 is increased in osteoglophonic dysplasia, which is caused by activating mutations in FGFR1." (PMID 25089825, 2014). "An increase in serum FGF23 has been reported for one case of a rare genetic hypophophatemic disorder called osteoglophonic dysplasia (OGD) caused by a dominant activating FGFR1 mutation." (PMID 23451204, 2013). "Support derives from the fact that FGF23 overproduction is a characteristic feature of osteoglophonic dysplasia, a rare form of dwarfism due to gain-of-function FGFR1 mutations." (PMID 36943390, 2023). "Similarly, Y372C missense gain-of-function mutation in FGFR1 in osteoglophonic dysplasia (OGD) and systemic administration of activating antibodies to FGFR1 in mice elevate circulating FGF23 levels, but have the confounding effects of activation of FGFRs in both bone and kidney." (PMID 25089825, 2014).
polycystic kidney disease (8 papers, 2012 to 2026). A usually autosomal dominant and less frequently autosomal recessive genetic disorder characterized by the presence of numerous cysts in the kidneys leading to end-stage renal failure. "This contrasts to the expression of FGF-23 in the renal epithelium that is observed in polycystic kidneys that is thought to be induced by inflammation." (PMID 30120363, 2018). "Pkd1 mutations in mouse models also cause abnormalities of the skeleton and human subjects with polycystic kidney disease appear to have earlier elevation of the bone-derived hormone FGF23." (PMID 23029375, 2012). "Notably, in one study utilizing the Han:SPRD (cy/+) rat model and an inducible PKD1 animal model of polycystic kidney disease (PKD), FGF-23 levels were increased, while tissue levels of Klotho did not exhibit any significant differences." (PMID 37985930, 2024).
sarcopenia (8 papers, 2020 to 2025). Progressive decline in muscle mass due to aging which results in decreased functional capacity of muscles. "Higher serum FGF23 levels were associated with stronger handgrip strength and lower odds of having sarcopenia in maintenance haemodialysis patients." (PMID 40464156, 2025). "Linear and logistic regression analyses were performed to examine the associations between FGF23 and muscle‐related parameters and sarcopenia, respectively." (PMID 40464156, 2025). "Elevated serum FGF23 was significantly associated with stronger handgrip strength and a lower incidence of sarcopenia." (PMID 40464156, 2025). "Clearly, more human studies in various scenarios of systemic FGF23 elevations and sarcopenia are needed to determine a potential association between both events." (PMID 38791164, 2024). "Thus, sarcopenia resulting from an inflammatory status linked to FGF23 becomes the more plausible explanation for this finding." (PMID 35612845, 2022). "We conducted this study to determine the prevalence of sarcopenia and to investigate the relationship between FGF23 and sarcopenia in a well‐characterised cohort of maintenance dialysis patients." (PMID 40464156, 2025). "Many bone-derived factors have been discovered, but here, we mainly focus on four bone factors that have a regulatory effect on muscles, namely, osteocalcin, IGF-1, RANKL and FGF-23, and seek to understand their possible therapeutic targets in sarcopenia." (PMID 34650980, 2021). "Moreover, we identified a significant positive association between FGF23 levels and handgrip strength, suggesting that FGF23 could potentially serve as a serum biomarker for sarcopenia in dialysis patients." (PMID 40464156, 2025). "Furthermore, a longitudinal study in 75-year-old women showed that high serum FGF23 levels are associated with reduced muscle strength and physical performance, but not with recued muscle mass and sarcopenia." (PMID 38791164, 2024). "Furthermore, it is likely that FGF23 has indirect effects on skeletal muscle, as FGF23 is interconnected with various established mechanisms of CKD-associated sarcopenia, such as the induction of local and systemic inflammation, of oxidative stress, and of abnormalities in adipokine metabolism." (PMID 38791164, 2024). "Third, since this is an exploratory study and not conducted to specifically investigate the association between phosphorus regulation and sarcopenia, we did not study factors influencing phosphorus regulation, such as FGF23, klotho, vitamin D, parathyroid hormone, and dietary intakes." (PMID 32438707, 2020). "In OP and sarcopenia, endocrine-derived FGFs (FGF19, FGF21, and FGF23) modulate bone mineral synthesis and decomposition as well as muscle tissues." (PMID 38902808, 2024). "The pro-longevity effects of Klotho have been partially attributed to modulation of fibroblast growth factor 23 (FGF23), Wnt, and mTOR pathways, several of which have also been a targets in sarcopenia research." (PMID 33876724, 2021). "In this review, we comprehensively summarized the latest research progress on the effects of the bone-derived cytokines FGF-23, IGF-1, RANKL, and osteocalcin on muscle and the prospects for treatment of sarcopenia." (PMID 34650980, 2021). "Herein, we comprehensively summarize the latest research progress on the effects of the osteokines FGF-23, IGF-1, RANKL and osteocalcin on muscle to explore whether these cytokines can be utilized to treat and prevent sarcopenia." (PMID 34650980, 2021). "However while FGF23 activates this pathway to induce pathologic cardiac remodeling, there is currently no experimental evidence that FGF23 also does so to drive sarcopenia." (PMID 38791164, 2024).
type 1 diabetes (8 papers, 2015 to 2024). "Association between FGF23 and eGFR in patients with type 1 diabetes." (PMID 36084108, 2022).
acute coronary syndrome (7 papers, 2019 to 2022). Signs and symptoms related to acute ischemia of the myocardium secondary to coronary artery disease. "Data from the clinical studies support the important role of FGF23/Klotho/Wnt pathway cross-talk, where it was shown that in patients on hemodialysis elevated serum FGF23 with lower sKlotho and sclerostin, may act as a predictor of CV complications (LVH, acute coronary syndrome, arrhythmias, etc.)." (PMID 34065339, 2021).
liver disease (7 papers, 2013 to 2025). "Elevated systemic FGF23 levels are associated with poor liver disease prognosis, while the transforming growth factor (TGF)-β, also bone-derived, inhibits hepatocyte proliferation and promotes fibrosis." (PMID 40430063, 2025). "Similar to findings with renal diseases, increases in systemic FGF23 have been linked to a poor prognosis in liver disease." (PMID 35231062, 2022). "Thus, it would be valuable to exam the glucose lipid metabolism and inflammatory microenvironment in liver of bone-specific FGF23 knockout mice and validate the association between FGF23 and various liver diseases in clinical study." (PMID 37091847, 2023). "Hepatic production of FGF23 was previously reported in autosomal dominant polycystic kidney disease, childhood biliary atresia and end-stage liver disease patients." (PMID 38479224, 2024). "Although FGF23 is involved in the regulation of bone-liver axis, it has received less attention in liver diseases than in kidney disease." (PMID 37091847, 2023). "The interesting possibility of the hormonal effects of hepatic FGF23 mediating the crosstalk between liver and other organs in hepatic diseases requires further study." (PMID 35231062, 2022). "The studies identify FGF23 as a potential new autocrine or paracrine regulator of liver disease." (PMID 35231062, 2022). "FGF23 concentration correlated with MELD score and sodium serum concentration suggesting that it may be associated with the severity of the liver disease." (PMID 23825530, 2013). "To determine if FGF23 plasma concentration is increased in patients with advanced liver disease and if it could be a marker of prognosis, we measured FGF23 plasma levels in patients on a waiting list for liver transplantation." (PMID 23825530, 2013). "How FGF23 may modulate liver disease and its outcome are unclear." (PMID 35231062, 2022). "FGF23 levels were independent of the cause of the liver disease." (PMID 23825530, 2013). "In addition, the promotion of inflammation in nonhepatic organs by hepatic FGF23 may result in the release of other proinflammatory factors from these organs which in turn trigger the progression of liver disease." (PMID 35231062, 2022). "Whether liver was the source of FGF23 in these conditions was not examined, but our mouse studies suggest that the liver itself could be the tissue responsible for FGF23 production in human liver diseases." (PMID 35231062, 2022). "To confirm this point we compared FGF23 plasma concentration measured in the patients on the waiting list with that measured in 384 subjects (222 males, median age 50 years, range 16–85 years) without liver disease investigated in our department with the same procedure during the same period." (PMID 23825530, 2013).
osteoarthritis (7 papers, 2008 to 2025). A noninflammatory degenerative joint disease occurring chiefly in older persons, characterized by degeneration of the articular cartilage, hypertrophy of bone at the margins and changes in the synovial membrane. "Furthermore, several inflammatory diseases such as inflammatory bowel disease (IBD), osteoarthritis, axial spondylorarthritis, lupus nephritis, psorasis, and AKI are associated with elevated FGF23 levels." (PMID 33416083, 2021). "Additionally, high levels of FGF23 may promote the Wnt/ß-catenin pathway in chondrocytes which activates the genes responsible for increased chondrocyte differentiation and osteoarthritis progression." (PMID 33681179, 2020). "For example, chondrocytes from patients suffering from osteoarthritis have elevated FGF23 gene expression levels, while children, who were in an acute phase of IBD, have elevated circulating FGF23 levels that decreased again in the remission phase." (PMID 33416083, 2021). "In addition we detected novel proteins that were deregulated in osteoarthritis, such as SOX11, FGF23, KLF6, WWOX and GDF15." (PMID 19011694, 2008). "Proteins such as SOX11, FGF23, KLF6, WWOX and GDF15 not implicated previously in the genesis of osteoarthritis were identified." (PMID 19011694, 2008). "This would also apply if calcification of soft tissues (e.g., ligaments) was directly related to excess FGF23 and its effect on target tissues, otherwise, if spinal stenosis is primarily related to osteoarthritis in the spine, it would likely not be amenable to treatment with burosumab." (PMID 37547321, 2023). "Thus starting treatment with burosumab only in adulthood will presumably not halt or reverse already developed osteoarthritis; but it may limit consequences of FGF23 excess on cartilage and prevent joint degeneration in case treatment is started before osteoarthritis is at an advanced stage." (PMID 37547321, 2023).